MIR195 (microRNA 195)
Synonyms: hsa-mir-195; MIRN195; miRNA195; mir-195
Gene: MicroRNA gene on chromosome 17 (7,017,615 to 7,017,701, reverse strand). Ensembl gene ENSG00000284112.
Gene Ontology:
Biological process: miRNA-mediated post-transcriptional gene silencing
Cellular component: RISC complex
Homologues: Orthologues: chimpanzee ptr-mir-195 (100% identical), macaque mml-mir-195 (99% identical), rat Mir195 (93% identical), guinea pig MIR195 (90% identical), mouse Mir195a (89% identical), pig ssc-mir-195 (80% identical), dog MIR195 (67% identical), zebrafish mir457a (60% identical). Paralogues in human: MIR16-2 (55% identical), MIR15B (47% identical), MIR15A (43% identical).
Diseases named in the same sentence as MIR195 in open-access papers:
MIR195 is named in the same sentence as 5 diseases in open-access papers, as found by Europe PMC text mining. Sharing a sentence is not in itself a finding about the gene and the disease. The quoted sentences say what the papers report.
diabetes (1 paper, 2024). "Therapeutic silencing of MIR195 improves myocardial function in diabetes by reducing oxidative damage, inhibiting apoptosis, and promoting endothelial cell angiogenesis." (PMID 38256676, 2024).
type 2 diabetes (1 paper, 2024). "Analysis using the Mann–Whitney U test showed a statistically significant (p < 0.05) difference in the expression of MIR1-1 (p = 0.031) and MIR195 (p = 0.042) associated with the occurrence of type 2 diabetes in the subjects." (PMID 38256676, 2024). "The value of MIR195 gene expression was statistically significantly higher in patients with type 2 diabetes (median: 0.389, mean: 0.442; standard deviation: 0.819) compared to patients without type 2 diabetes (median: −0.027; mean: 0.08; standard deviation: 0.942)." (PMID 38256676, 2024).
cardiovascular diseases (1 paper, 2024). "MIR195 plays an important role in regulating cardiovascular diseases." (PMID 38256676, 2024).
MIR195 also shares sentences with these, for which no sentence is quoted: cancer (1 paper); tumour (1).